PTH (parathyroid hormone)
Diseases named in the same sentence as PTH in open-access papers (continued):
Sharing a sentence is not in itself a finding about the gene and the disease.
Hypercalcemia (continued). "Changes in mineral metabolism after vitamin D intoxication included hypercalcemia (12.0 ± 0.3 mg/dL), hyperphosphatemia (6.3 ± 0.4 mg/dL), increased plasma calcidiol (381.5 ± 28.2 ng/mL) and decreased plasma parathyroid hormone (1.2 ± 0.7 pg/mL)." (PMID 27243456, 2016). "Most of the patients present with clinical and biochemical manifestations of severe hyperparathyroidism, including severe hypercalcemia, elevated parathyroid hormone (PTH) level as well as renal and osseous complications." (PMID 26658808, 2016). "Hypercalcemia, an adverse effect of PTH treatments, and concerns about osteosarcoma development are also limitations for PTH therapies." (PMID 26941261, 2016). "Calcium sensitivity is reduced in parathyroid tumor cells, i.e.the calcium–PTH set point is rightward shifted, allowing for persistent PTH secretiondespite relative hypercalcemia." (PMID 26865585, 2016). "Tertiary hyperparathyroidism, with an increase of the set-point calcium-PTH and frequent hypercalcemia, represents the response of the autonomous function of one or more parathyroid glands to long-standing SHPT." (PMID 27756251, 2016). "The biochemical investigations were carried out and showed marked hypercalcaemia (15.70 mg/dL, range 8.60–10.20 mg/dL) and an elevated parathyroid hormone (PTH) concentration (1472.00 pg/mL, range 16–87 pg/mL) in the blood." (PMID 26881146, 2016). "This hypercalcemia caused relative PTH suppression instead of total suppression as would be expected in non-PTH mediated hypercalcemia outside of renal failure." (PMID 27683096, 2016). "Laboratory investigations revealed hypercalcemia (2.89 mmol/L), hypophosphatemia (0.78 mmol/L) and elevations in parathyroid hormone (PTH) (15.2 pmol/L)." (PMID 27756384, 2016). "In lynx with renal disease, that had more severe hypercalcemia and lower PTH, calcitriol was lower than in healthy captive lynx but was not decreased when compared with free ranging lynx." (PMID 27243456, 2016). "The patient persisted with hypercalcemia and elevated levels of PTH during the first 6 months of clinical follow-up; thus, she was sent to our Medical Unit for additional evaluation." (PMID 27525132, 2016). "The laboratory examination reported hypercalcemia with inhibited PTH and hypoglycemia with inhibited insulin secretion, arriving to the conclusion of tumoral peptide production." (PMID 27737327, 2016). "A patient with anal squamous cell carcinoma was admitted with hypercalcemia, suppressed PTH and hypophosphatemia." (PMID 26998187, 2016). "Once the soft tissue deposits disappeared, the hypercalcemia and relative PTH suppression resolved, which was observed at 2 months following discharge from hospital." (PMID 27683096, 2016). "He presented with hypercalcemia, low levels of parathyroid hormone (PTH), and very high serum 25-hydroxyvitamin D (25-OHD) levels." (PMID 27478669, 2016). "Primary hyperparathyroidism is characterized by enlarged parathyroid glands due to an adenoma (80–85 %) or multiglandular disease (~15 %) causing hypersecretion of parathyroid hormone (PTH) and generally hypercalcemia." (PMID 26973719, 2016). "The most common PTH-independent mechanisms for hypercalcemia are related to malignancies, with many different contributing mechanisms." (PMID 26213611, 2015). "Our investigation revealed that the clinico-biochemcial diagnosis of CSS was present in one-fifth of hospitalized patients with PTH-independent hypercalcemia." (PMID 26239247, 2015). "Diagnosis of CSS was based on the presence of hypercalcemia; a normal parathyroid hormone (PTH) level; renal insufficiency; metabolic alkalosis; a history of calcium intake; and documented improvement with treatment." (PMID 26239247, 2015). "In PTH mediated hypercalcemia the two differential diagnoses to consider are primary hyperparathyroidism and familial hypocalciuric hypercalcemia." (PMID 26199627, 2015).
Hypercalcemia (continued). "Seventy-two of the 429 patients (16.8%) were identified with hypercalcemia accompanied by a normal or low PTH." (PMID 26239247, 2015). "The most common presenting complaint was asymptomatic incidental hypercalcemia with elevated parathyroid hormone, but presentations ranged from osteopenia to renal failure." (PMID 26521153, 2015). "The hypercalcemia observed in both models is likely due to early elevated PTH levels and aggravated by 1,25-dihydroxy vitamin-D3-facilitated intestinal Ca2+ absorption." (PMID 26566277, 2015). "PTH administration induced hypercalcemia in fugu (Tetraodon nigrividans) by inducing both osteoblast and osteoclast function and by decreasing scale calcium content." (PMID 26061167, 2015). "An elevated 1,25 vitamin D level in non-PTH mediated hypercalcemia indicates lymphoma or granulomatous disease." (PMID 26199627, 2015). "Prolonged, uncontrolled PTH secretion will result in downregulation of PTH receptors so that a higher plasma calcium level is needed to suppress PTH, resulting in hypercalcaemia." (PMID 25543193, 2015). "PHPT results from inappropriate overproduction of parathyroid hormone from one or many parathyroid glands and presents with hypercalcemia." (PMID 25893124, 2015). "Elevated urinary calcium in a patient with PTH mediated hypercalcemia signifies primary hyperparathyroidism." (PMID 26199627, 2015). "Normally, hypercalcemia suppresses release of PTH and thus calcitriol production; however, in sarcoidosis, activated macrophages produce calcitriol independent of PTH." (PMID 26199627, 2015). "The symptoms of nonfunctioning cysts are limited to those caused by compression of neighbouring structures whereas the problems associated with functioning cysts are related to excessive secretion of PTH and subsequent hyperparathyroidism and hypercalcaemia." (PMID 26064758, 2015). "Overall, 6 patients achieved PTH levels within the target range while values remained elevated in the remainder due to the development of hypercalcemia and hyperphosphatemia." (PMID 25774916, 2015). "Both cases were diagnosed parathyroid adenoma with extracapsular bleeding by hypercalcemia, high levels of intact parathyroid hormone and presence of a nodule behind the thyroid." (PMID 26610856, 2015). "Of the 72 patients with non-PTH mediated hypercalcemia, 15 (20.8%) satisfied all the criteria for the diagnosis of CSS." (PMID 26239247, 2015). "The diagnostic work-up demonstrated primary hyperparathyroidism with hypercalcemia of 13.36 mg/dL, a PTH level of 2551 pg/mL, bone brown tumors, and microcalcifications within pancreas and kidneys." (PMID 26640724, 2015). "Biochemical assays revealed hypernatremia (149 mmol/L), severe hypercalcemia (4.08 mmol/L), hypophosfatemia (0.62 mmol/L), elevated levels of PTH (252 ng/L), reduced vitamin D (32 nmol/L) and slight renal failure (urea 8.7 mmol/L, creatinine 112 μmol/L)." (PMID 25631825, 2015). "When encountering cervical and/or mediastinal hematoma, blood testing, which can detect hypercalcemia and a high level of intact PTH, is one of the key examinations for investigating the possibility of parathyroid adenoma bleeding." (PMID 26610856, 2015). "The patient reported was paradoxical because in case of hypercalcemia, PTH levels would tend to be low or, in typical hyperparathyroidism, they would be high." (PMID 25003934, 2014). "Crh−120/+ mice also had low bone mineral density, hypercalcemia, hypercalciuria, and decreased concentrations of plasma PTH and osteocalcin." (PMID 24302625, 2014). "The laboratory tests for bone metabolism were inconclusive, and PTH inappropriately persisted with “normal” levels even with hypercalcemia." (PMID 25003934, 2014). "The causes of hypercalcemia that result in elevated parathyroid hormone level are few including familial benign (hypocalciuric) hypercalcemia (FHH), lithium-induced hypercalcemia, and tertiary hyperparathyroidism." (PMID 25254042, 2014).
Hypercalcemia (continued). "In this condition, PTH is typically suppressed by high calcium levels and hypercalcemia occurs due to PTH-independent extrarenal production of 1,25 dihydroxy-vitamin D from 25-hydroxyvitamin D by activated mononuclear cells." (PMID 24572248, 2014). "Excess parathyroid hormone (PTH) secretion leads to hypercalcemia, hypophosphatemia, nephrocalcinosis, nephrolithiasis, and decreased bone density." (PMID 24592349, 2014). "Primary hyperparathyroidism (PHPT) is characterized by inappropriately elevated or normal PTH in presence of hypercalcemia." (PMID 25254042, 2014). "In homozygous cases, the patients present with excessive hypercalcemia and increased PTH levels in the neonatal period." (PMID 25241609, 2014). "This point mutation, inherited in heterozygosity and implicated in inactivating CaSR, leads to a loss of function of the receptor, with evidence, in the father, of hypercalcemia and unsuppressed PTH levels." (PMID 25292184, 2014). "In this case, the bitemporal hemianopsia and diplopia along with the severe hypercalcemia and high PTH levels were the clues for the diagnosis." (PMID 25276444, 2014). "Cinacalcet is a calcimimetic that acts on the calcium-sensing receptor of parathyroid cells, reducing parathyroid hormone and attenuating hypercalcemia." (PMID 24524553, 2014). "The patient had persistent hypercalcemia after surgical removal of parathyroid adenoma with recorded significant decrease in PTH level." (PMID 24716007, 2014). "According to our experience, the presence of extraskeletal calcification, calciphylaxis, debilitating bone disease, refractory pruritus, severe hypercalcemia, and PTH >1600 ng/L are strong indications for surgical treatment." (PMID 24886230, 2014). "Elevated 1,25 dihydroxy-vitamin D levels lead to increased intestinal absorption and increased bone resorption of calcium, resulting in hypercalcemia, hypercalcuria, nephrocalcinosis and kidney stones, as well as decreased parathyroid hormone levels." (PMID 24572248, 2014). "A 38-year-old patient presented to our clinic with a history of bilateral nephrolithiasis, chronic hypercalcaemia, and PTH elevation." (PMID 24685256, 2014). "The Crh−120/+ mice illustrated this by having a low BMD, hypercalcemia, hypercalcuria, and decreased plasma concentrations of PTH and osteocalcin." (PMID 24302625, 2014). "Laboratory studies performed during the emergency room visit identified hypercalcemia (13.1 mg/dL; normal range 8.9–10.7) and hypophosphatemia (2 mg/dL; normal range 3.0–5.2), with a concomitant intact PTH of 154 pg/mL (normal range 9–69)." (PMID 24592349, 2014). "We considered the diagnosis of hypercalcemia of malignancy with elevated calcium levels and suppressed PTH level with the existence of skeletal bone metastasis and the absence of parathyroid gland pathology." (PMID 25024705, 2014). "Hypercalcemia occurs because tumor-produced PTHrP interacts with the renal and bone PTH/PTHrP receptor." (PMID 25197285, 2014). "The steady state and transient PTH secretion responses of the model are in agreement with human experimental PTH responses to different hypocalcemia and hypercalcemia stimuli." (PMID 24744900, 2014). "This is a case of a novel inactivating point mutation of CaSR gene that determines an atypical clinical presentation of FHH, characterized by hypercalcemia, hypercalciuria and inadequate normal PTH levels." (PMID 25292184, 2014). "In the Crh−120/+ mice, it is likely that the hypercalcemia resulted in a suppression of PTH secretion." (PMID 24302625, 2014). "Laboratory examinations revealed hypercalcemia, hypophosphatemia and an increased intact parathyroid hormone level." (PMID 24959251, 2014). "We suggest that in any patient presenting with persistent vomiting and hypercalcemia, particularly in the presence of normal parathyroid hormone, a diagnosis of overdose of vitamin D should be suspected." (PMID 24571630, 2014).
Hypercalcemia (continued). "WT-SPR4 mice developed hypophosphatemia and hypercalcemia with increased PTH, FGF23 and 1.25(OH)2D3." (PMID 24839967, 2014). "Patients with hypercalcemia of malignancy, secretion of endogenous parathyroid hormone (PTH) itself is suppressed by the PTHrP-mediated hypercalcemia." (PMID 26328223, 2014). "Parathyroid adenomas release excessive quantities of parathyroid hormone (PTH), which can lead to hypercalcemia, osteoporosis, skeletal fractures, kidney stones, and nephrocalcinosis." (PMID 25594030, 2014). "The steady state and transient PTH secretion responses of the model are in agreement with human experimental PTH responses to different hypo and hypercalcemia stimuli." (PMID 24744900, 2014). "Clinically hypercalcemia with intact serum parathyroid hormone levels within or above the upper limits of normal and increased parathyroid cell mass suggest a diagnosis of primary hyperthryroidism." (PMID 24106573, 2013). "Primary hyperparathyroidism (PHPT) is an endocrine disease characterized by hypercalcemia attributable to autonomous overproduction of parathyroid hormone (PTH)." (PMID 23777622, 2013). "All three cases presented with hypercalcemia symptoms and had characteristic laboratory findings such as hypercalcemia, hypercalciuria, low levels of parathyroid hormone." (PMID 23748070, 2013). "Both intact PTH (immunochemiluminometric assay) and PTHrP (immunochemiluminometric assay) were appropriately low for his hypercalcemia." (PMID 23476827, 2013). "Thyroidectomized FX rats showed hypercalcemia, normal level of calcitonin, and decreased level of PTH." (PMID 23776526, 2013). "This binding results in a lower threshold for the secretion of PTH, implicating that the serum calcium is also higher in all lithium users, and leading to hypercalcemia in approximately 15%." (PMID 25505684, 2013). "Re-evaluation at 16 weeks revealed hypercalcemia, worsening of the hypophosphatemia, persistence of the elevated parathyroid hormone (PTH) along with normalization of serum 25-hydroxy-vitamin-D [25(OH)D]." (PMID 24379038, 2013). "Increased PTH production leads to hypercalcemia via bone resorption, increased gastrointestinal absorption of calcium, increased production of vitamin D3 and reduced renal calcium clearance." (PMID 24106573, 2013). "Total >50% decrease of PTH within 20 minutes was obtained in 168/188 patients (89.4%); postoperative normal calcemia and PTH were found in 167 patients and persistent postoperative hypercalcemia with increased value of PTH was found in 1 patient." (PMID 24044556, 2013). "The K/DIGO guidelines suggest bone biopsy for unexplained fractures, persistent bone pain, unexplained hypercalcemia, high PTH but low alkaline phosphatases, and before therapy with bisphosphonates." (PMID 24501586, 2013). "It is recommended that the use of calcium-based phosphate binders should be restricted in patients with hypercalcemia, vascular calcification, low levels of PTH, or adynamic bone disease." (PMID 23525083, 2013). "Following oral Ca challenge, thyroid-intact FX rats showed hypercalcemia, decreased levels of serum gastrin, increased level of calcitonin and decreased level of PTH." (PMID 23776526, 2013). "Re-evaluation due to lack of clinical improvement following vitamin-D and calcium supplementation revealed hypercalcemia 11.9 mg/dL, normal 25(OH)D 41 ng/mL, persistence of elevated PTH 632 pg/mL." (PMID 24379038, 2013). "Physiologically, hypercalcaemia from high intestinal Ca absorption results in a reduced secretion of parathyroid hormone (PTH)." (PMID 23940588, 2013). "(c) Increase calcitriol dose by 1 ng/kg/day until PTH is controlled (within normal range or ionized hypercalcemia occurs." (PMID 23566108, 2013). "On the other hand, in patients with HHRH due to hypophosphatemia, an appropriate elevation in the serum levels of 1,25-dihydroxyvitamin D leading to hypercalciuria, hypercalcemia and decreased serum PTH levels and increased serum ALP activity are noted." (PMID 22672866, 2012).
Hypercalcemia (continued). "An earlier Finish study reported winter hypercalcaemia and a blunted PTH response in MS patients compared to controls." (PMID 23202962, 2012). "Hypophosphatemia was present in 34% of the patients, hypercalcemia in 3%, and elevated PTH levels in 66%." (PMID 22811905, 2012). "There are plenty of etiologies to induce hypercalcemia in cancer patients, such as osteoclastic metastases to bone, secretion of parathyroid hormone (PTH)- related peptides by tumor cells, or excessive vitamin D produced by tumors." (PMID 22280526, 2012). "It usually presents with symptoms of hypercalcaemia as a result of the increased secretion of parathyroid hormone (PTH) by the adenoma." (PMID 23251179, 2012). "The high prevalence of LVH in PHPT patients has been attributed, in part, to effects of PTH and/or hypercalcemia." (PMID 22719761, 2012). "Both Klotho knockout (Kl−/−) and Fgf23 knockout (Fgf23−/−) mice exhibit hypercalcemia, hyperphosphatemia with low to undetectable PTH levels, and severe osteomalacia." (PMID 22615584, 2012). "In conclusion the preoperative evaluation of a patient with severe hypercalcemia and high PTH levels should include the possible diagnosis of parathyroid carcinoma, especially in symptomatic patients or in case of palpable neck mass." (PMID 23050135, 2012). "The prevalence of hypophosphatemia was 34%, hypercalcemia 3%, and elevated PTH levels 66%, at a median (25th–75th percentile) duration of 12.8 (7.5–30.9) months post-transplant." (PMID 22811905, 2012). "HHRH is an autosomal recessive form of hypophosphatemia that has been recently described with hyperphosphaturia, hypercalciuria, hypercalcemia, decreased serum parathormone (PTH) levels and increased serum alkaline phosphatase (ALP) activity." (PMID 22672866, 2012). "The infant had a combination of mild hypercalcemia, mildly elevated serum magnesium, inappropriately high-normal PTH and low urinary calcium creatinine clearance." (PMID 22620673, 2012). "It is proposed that malignant cells of the primary colon tumor and distant metastases, in this patient, were the site of ectopic PTH-rp secretion resulting in hypercalcemia." (PMID 29147304, 2012). "The phenotypes of Fgf23−/− and Klotho−/− (Kl−/−) mice are very similar and include hypercalcemia, hyperphosphatemia, hypervitaminosis D, suppressed PTH levels, and severe osteomalacia/osteoidosis." (PMID 22615584, 2012). "A markedly elevated intact PTH with mild hypercalcemia and hypermagnesemia were noted on presentation." (PMID 22620673, 2012). "Although most cases of severe hypercalcemia are seen in malignancy, it is important to emphasize that severe hypercalcemia with raised PTH is pathognomonic of primary hyperparathyroidism." (PMID 22840059, 2012). "Newer evidence suggests that the CaSR plays a role independently of parathyroid hormone in the renal tubules to promote calcium secretion in the face of hypercalcemia." (PMID 21747852, 2011). "Reduction of hypercalcemia in the CaR−/− mice was the common biochemical alteration induced by deleting the 1α(OH)ase in the CaR−/−1α(OH)ase−/− mice and PTH in the CaR−/−PTH−/− mice." (PMID 21966280, 2011). "Sporadic primary hyperparathyroidism (PHPT) is an endocrine disorder usually characterized by persistent fasting hypercalcaemia attributable to autonomous overproduction of parathyroid hormone (PTH) by parathyroid adenoma or hyperplasia (hypercalcaemic PHPT)." (PMID 21423544, 2011). "Primary hyperparathyroidism (PHPT) is a disease characterized by hypercalcemia due to autonomous production of parathyroid hormone (PTH)." (PMID 21747854, 2011). "Suggested mediators have included hypercalcemia, high PTH, plasma renin, renal functions, uric acid, and BMI." (PMID 21403888, 2011). "Tertiary hyperparathyroidism occurs in patients with long-standing secondary hyperparathyroidism who develop autonomous PTH production with hypercalcemia." (PMID 21747852, 2011).